BRAF (B-Raf proto-oncogene, serine/threonine kinase)
Diseases named in the same sentence as BRAF in open-access papers (continued):
Sharing a sentence is not in itself a finding about the gene and the disease.
lymph node metastasis (198 papers, 2011 to 2026). "LASSO regression identified eight predictors: age, tumor size, extrathyroidal extension, lymph node metastasis, BRAF V600E mutation, postoperative stimulated thyroglobulin (sTg) level, radioactive iodine dose, and TNM stage." (PMID 41877795, 2026). "In contrast, the literature shows a well-established association between increased mean BRAF V600E AF and lymph node metastasis in PTC." (PMID 40805249, 2025). "The BRAF V600E mutation was associated with extrathyroidal extension, lymph node metastases, and a higher rate of biochemical incomplete response to therapy (HR = 2.43; 95% CI: 1.21–5.23; P = 0.016)." (PMID 41368991, 2025). "Studies indicate that genes like BRAF are associated with an increased risk of extrathyroidal extension, lymph node metastasis, advanced disease, and recurrence." (PMID 40034225, 2025). "These patients tend to be younger, are more often women, have lower rates of lymph node metastasis and capsular invasion, and have a lower incidence of BRAF mutations." (PMID 41282299, 2025). "Previous studies have verified that patients with PTC frequently carry the BRAF mutation, with prevalence rates reaching 73.4%, while aggressive behaviors, such as capsule invasion, vessel invasion and lymph node metastasis are linked to the BRAF mutation." (PMID 40028210, 2025). "This again contrasts the behavior of BRAF V600E mutations which have been associated with 2–3x increased risk of lymph node metastasis." (PMID 40075589, 2025). "Patients with KRAS mutations exhibited a higher rate of overall distant organ metastasis (70.3%), including metastasis to the liver (44.1%) and lungs (19.8%), whereas patients with BRAF mutations showed a higher rate of lymph node metastasis (82.4%)." (PMID 40075837, 2025). "The dataset included demographics, pathomorphological (e.g., sex, age, BRAF mutation status, lymph node metastasis), and ultrasound characteristics (e.g., nodule location, microcalcification, diameter)." (PMID 40282484, 2025). "A recent meta-analysis reported a significantly increased risk of multifocality, extrathyroidal invasion, local and distant lymph node metastases, recurrence, and decreased 10-year survival in papillary microcarcinomas carrying the BRAF V600E mutation." (PMID 39456495, 2024). "Among the cases with BRAF mutations, the incidence of lymph node metastasis is 68.3%, significantly higher than other gene mutation groups." (PMID 38277563, 2024). "Previous studies have shown that BRAF V600E is associated with adverse factors such as lymph node metastasis and local recurrence." (PMID 39135992, 2024). "The presence of BRAF-mutated ctDNA was correlated with higher stage, extrathyroidal extension, lymph node metastasis (LNM), and distant metastasis." (PMID 39336882, 2024). "on the correlation between BRAF mutation and lymph node metastasis and recurrence of papillary thyroid microcarcinoma also reported similar results." (PMID 39363900, 2024). "Preoperative mutation testing for BRAF V600E is conducted, and a positive result often suggests malignancy of the thyroglossal cyst, frequently associated with lymph node metastasis." (PMID 38941410, 2024). "Genetic mutations in BRAF V600E are linked to higher disease-specific mortality, lymph node metastasis, extrathyroidal extension, an elevated risk of recurrence, distant metastasis, advanced disease stages, and older patient age." (PMID 39061714, 2024). "A statistically significant 18-fold lower avidity was observed in BRAF-mutated lymph node metastases (CI 3.9–87)." (PMID 37352166, 2023). "BRAF-mutated metastatic CRCs (mCRCs) are also associated with poorer survival outcomes and higher rates of distant lymph node metastases." (PMID 38201500, 2023). "Our analysis revealed a strong association between high BRAF V600E AF and a positive sentinel lymph node (p = 0.021), indicating that patients with high AF are more likely to have local lymph node metastasis." (PMID 38201541, 2023).
lymph node metastasis (continued). "According to several researchers, BRAF mutation is related to aggressiveness, such as lymph node metastases." (PMID 36817603, 2023). "Lymph node metastases with BRAF and TERT promoter mutations were found to exhibit lower iodine avidity, with differences higher than previously reported." (PMID 37352166, 2023). "Meta-analysis revealed that BRAF mutation is associated with lymph node metastasis, tumor stage, extrathyroidal extension, tumor size, and classic PTC." (PMID 36070149, 2023). "Primary tumors with any BRAF mutation developing lymph node metastasis had also significantly lower miR-125b, miR-200c and miR-205 (p-value 0.0499, 0.0268 and 0.017, respectively) compared to tumors not presenting lymph node metastasis." (PMID 35326682, 2022). "Our results also showed that BRAF mutations were highly associated with extra-thyroidal invasion and lymph node metastasis." (PMID 36160023, 2022). "Our study showed that patients with the most common mutation of BRAF had a lateral lymph node metastasis rate of 22.2%." (PMID 35865459, 2022). "In the present study, we found strong correlations between Ref-1 high expression and BRAF mutation, lymph node metastasis, and TNM stage." (PMID 35136031, 2022). "In our study, patients with PTC tumors over 1 cm harboring BRAF V600E mutation had higher rates of lymph node metastasis, multifocality, and extra-thyroid extension." (PMID 35197932, 2022). "Patients with BRAF mutations are more likely to have regional lymph node metastases and ulceration in the primary lesion." (PMID 35406444, 2022). "The rates of lymph node metastases, multifocality, and extra-thyroid extension were significantly increased with larger sizes harboring BRAF V600E mutation." (PMID 35197932, 2022). "Compared with PTMC harboring WT-BRAF, PTC harboring BRAF V600E mutation had a crude OR of 2.55 (1.06–6.12, p = 0.036) for lymph node metastasis and remained significant after adjustment for age and gender [3.01 (1.26–8.68), p = 0.015]." (PMID 35197932, 2022). "We found that hypoechogenicity was highly associated with BRAF gene mutations, while lymph node metastasis was least associated with BRAF gene mutations." (PMID 36160023, 2022). "An association between BRAF mutation positivity and aggressive tumor phenotype (extrathyroidal extension, lymph node metastasis) hes been reported, with a higher risk of recurrent and persistent disease, especially when TERT promoter mutation coexists." (PMID 34070605, 2021). "Carcinoma cells demonstrated intertumoral heterogeneity based on BRAF V600E mutation or lymph node metastasis, and some altered genes were identified to be correlated with disease-free survival in The Cancer Genome Atlas datasets." (PMID 34805166, 2021). "AHNAK2 expression was significantly high in patients with advanced stage, advanced T classification, lymph node metastasis, increased BRAF mutations and decreased RAS mutations." (PMID 32966238, 2020). "High tumor budding was associated with BRAF positivity, age over 55 years, lymph node metastasis, advanced AJCC stage, and disease progression (all p < 0.05)." (PMID 33256003, 2020). "Currently, many studies have shown that BRAF V600E mutation correlates with other factors of poor prognosis, including patient age, bigger tumor size, extracapsular invasion, multifocality, lymph node metastasis, distant metastasis and higher TNM stage." (PMID 32393293, 2020). "BRAF V600E mutation has been associated with more aggressive tumor characteristics, such as capsular invasion, lymph node metastasis, distal metastasis and recurrence." (PMID 32393293, 2020).
lymph node metastasis (continued). "These authors reported 46% vs. 24% for peritoneal metastasis when comparing BRAF mutated vs. BRAF wild-type respectively, 53% vs. 38% for lymph nodes metastases, and 35% vs. 49% for lung metastasis." (PMID 31952366, 2020). "BRAF mutation was more related with lymph node metastasis (p = 0.030), bowel wall invasion, mucin production (p = 0.010), tumor thrombus (p = 0.002), perineural invasion (p = 0.018), poor differentiation (p = 0.001) and MSI status including MSS/L and MSI-H." (PMID 32161617, 2020). "BRAF mutation is significantly correlated with large tumor size, positive surgical margins and lymph node metastasis suggesting an association between BRAFV600E mutation and tumor growth and spread." (PMID 32315324, 2020). "Presently, our meta-analysis provided strong evidence that BRAF V600E/TERT promoter mutations were significantly correlated with lymph node metastasis, multifocality, distant metastasis, tumor recurrence, extrathyroidal extension, and dead of disease." (PMID 31300059, 2019). "The percentage of BRAF mutant alleles was higher in PTCs presenting with lymph node metastases at the time of surgery, and BRAFV600E were detected in metastatic lesions." (PMID 31810221, 2019). "Meta-analysis showed significant association of BRAF V600E+/TERT+ co-mutations with lymph node metastasis, multifocality, distant metastasis, tumor recurrence, extrathyroidal extension, and dead of disease." (PMID 31300059, 2019). "In PTC, the BRAF V600E mutation is reportedly associated with extrathyroidal extension, multifocality, advanced cancer stage, lymph node metastasis, and recurrence." (PMID 31428052, 2019). "Despite a high survival rate, patients with certain clinicopathologic features have been associated with poorer prognosis, such as older age at diagnosis, gender, extrathyroidal invasion, BRAF V600E mutation status, and lymph node metastasis (LNM)." (PMID 29713312, 2018). "Previously, BRAF mutations were associated with older age, tall-cell variants, extrathyroidal extensions, positive surgical margins, lymph-node metastasis, and stage IV disease." (PMID 30285776, 2018). "Patients with TCV were associated with multifocality, higher TNM stage, extrathyroidal extension, vascular invasion, lymph node metastasis, distant metastasis, BRAF mutation, disease-specific survival, and overall survival." (PMID 28009980, 2017). "High incidences of peritoneal and distant lymph node metastases were observed in mCRC with BRAF V600E mutations." (PMID 29037218, 2017). "Lower UNC5D expression was significantly associated with aggressive tumor behaviors, such as lymph node metastasis and BRAF mutation." (PMID 29221192, 2017). "Presence of psammoma bodies was significantly associated with younger age (p < 0.001), lymph node metastasis (p < 0.001), BRAF V600E mutation (p = 0.001), and persistent/recurrent disease (p = 0.030)." (PMID 28358874, 2017). "Increased EHD2 mRNA expression level was associated with extrathyroidal extension (p < 0.001), pT3-4 (p < 0.001), lymph node metastasis (p < 0.001), higher risk of recurrence (p < 0.001), and BRAF V600E (p < 0.001)." (PMID 28358874, 2017). "Associations of alcohol consumption and DTC risk were classified according to patient age at diagnosis and clinicopathologic features, such as tumor size, lymph node metastasis, extrathyroidal extension, BRAF mutation and TNM staging." (PMID 26985827, 2016). "Lymph node metastasis was more commonly found in 51 tumors (53.7 %) with BRAFV600E mutation compared to 40 tumors (38.1 %) with wild type BRAF (P = 0.038)." (PMID 27387551, 2016). "Further, according to the present meta-analysis, the prevalence of lymph node metastasis was increased in patients with BRAF mutation, with an odds ratio of 1.45; increased risk was observed in 39 of 60 studies." (PMID 27600854, 2016).
lymph node metastasis (continued). "Data regarding TNM stage, multifocality, vascular invasion, lymph node metastasis, distant metastasis, and BRAF V600E mutations were reported in seven, four, four, nine, four, and five studies, respectively." (PMID 27833153, 2016). "According to our analysis, the association between the occurrence of lymph node metastasis and BRAF mutations was significant (p < 0.00001)." (PMID 27600854, 2016). "Associations were further examined in patient subgroups divided according to clinicohistologic characteristics, including histologic type, tumor size, lymph node metastasis, extrathyroidal extension, BRAF (V600E) mutation and TNM staging." (PMID 26985827, 2016). "Information regarding BRAF mutational status, histological subtype, clinical risk, presence of lymph node metastases, clinical tumor stage, presence of extra-thyroidal extension, age and gender were used to create different PCA plots." (PMID 26487287, 2015). "Several studies have shown a strong correlation between the presence of BRAF mutation and lymph node metastasis, extrathyroid extension, advanced stage (III and IV) on diagnosis, and disease recurrence." (PMID 26693224, 2015). "Multivariate logistic regression analysis showed that the BRAF V600E mutation (HR, 2.471; 95% CI, 1.149–5.312) and lymph node metastasis (HR, 3.003; 95% CI, 1.027–8.771) are independent factors that predict tumor prognosis." (PMID 24396464, 2014). "The results indicated that tumor persistence/metastasis was significantly associated with tumor size, lymph node metastasis and BRAF mutation in the univariate analysis." (PMID 24396464, 2014). "The other patient had a discordant BRAF mutation status between two regional metastases, that is, a BRAF wild-type lymph node metastasis and a BRAF-mutant skin metastasis." (PMID 25526463, 2014). "A recent meta-analysis has shown that BRAF is significantly associated with recurrence, lymph node metastasis, extra-thyroidal extension and advanced stage." (PMID 24839549, 2014). "Concurrent with other studies, lymph node metastasis and BRAF mutation were independent factors in the prediction of tumor prognosis in the multivariate logistic regression analysis." (PMID 24396464, 2014). "A large number of studies have demonstrated that the BRAF gene mutation is associated with pathological features, including patient age, extrathyroidal invasion, lymph node metastasis and tumor stage, which aid in determining patient prognosis." (PMID 24396464, 2014). "Meta-analyses argue that BRAF p.V600E predicts lymph node metastasis, but whether BRAF p.V600E is associated with PTC subtype, tumor size, loco-regional recurrence, and distant metastasis is not clear." (PMID 40237893, 2025). "Collectively, these studies – encompassing cohorts ranging from 2,500 to 25,000 patients approximately – consistently show that BRAF V600E is associated with disease recurrence and adverse pathological features such as extrathyroidal extension and lymph node metastases." (PMID 41368991, 2025). "BL BRAF V600E mutations were more likely to be detected if metastases occurred only in the liver (OR 15.87; P < 0.0001) or in more than one organ including the liver (OR 16.12; P < 0.0001), or if lymph node metastases were present (OR 6.11; P = 0.018)." (PMID 39630848, 2025). "Indeed, many studies have found that PTC with BRAF V600E mutation is associated with lymph node metastasis." (PMID 38734621, 2024). "BRAF-mutated tumors, particularly those harboring a V600E mutation, are associated with significantly poorer OS than BRAF-V600 wild-type tumors (median 10.4 versus 34.7 months), and a higher rate of peritoneal and distant lymph node metastasis." (PMID 40171464, 2024). "The presence of a BRAF mutation and overexpression of the Cyclin D1 protein have been predominantly observed in lymph node metastasis, suggesting that these factors may play an important role in metastasis." (PMID 39407879, 2024).
lymph node metastasis (continued). "Since HT can counteract the effect of BRAF mutation and neutralize the risk of lymph node metastasis in PTC patients, this specific subset of patients may maintain treatment as if harboring a wild type PTC." (PMID 37190300, 2023). "The lateral lymph node metastasis rate in this group of patients is also high (70%, 7/10), and they can be classified as a high-risk group clinically, but other clinical characteristics are significantly different from the BRAF+TERT group of patients." (PMID 35865459, 2022). "In addition, some scholars revealed that BRAF mutations were associated with markers of clinical aggressiveness such as larger tumors, lymph node metastases, and poor clinical outcomes." (PMID 35784530, 2022). "Furthermore, miR-222-3p ISH score and BRAF mutation status were used to predict lymph node metastasis of PTCs." (PMID 35651980, 2022). "In this study, independent risk factors for BRAF mutations were screened by multivariable logistic regression analysis, including microcalcifications, hypoechogenicity, lymph node metastases, lobulated margins, extra-thyroidal invasion, and vertical position (aspect ratio >1)." (PMID 36160023, 2022). "Studies have shown that, although the overall lymph node metastasis rate of patients with BRAF mutations is high, most are micro metastases in the central region, and may not affect the long-term prognosis." (PMID 35865459, 2022). "Compared with PTMC harboring wild type (WT)-BRAF, PTC harboring BRAF V600E mutation had adjusted higher ORs of 3.01 (1.26–8.68, p = 0.015), 3.20 (1.22–8.42, p = 0.018), and 5.62 (2.25–14.01, p < 0.001) for lymph node metastases, multifocality, and extra-thyroid extension, respectively." (PMID 35197932, 2022). "However, only a few studies have examined BRAF V600E mutation in metastases, such as lymph node metastasis (LNM)." (PMID 33064665, 2020). "Therefore, further studies are needed to establish the clinical utility of the BRAF V600E mutation as a predictive biomarker for lymph node metastasis in PTC." (PMID 31212879, 2019). "Age, lymph node metastasis, and 131I radiotherapy were risk factors for BRAF V600E mutation." (PMID 31300059, 2019). "The association of BRAF V600E mutation and lymph node metastasis in PTC remains controversial." (PMID 31212879, 2019). "The BRAF V600E mutation was marginally associated with lymph node metastasis (p = 0.054)." (PMID 31212879, 2019). "The BRAF V600 mutation status was assessed using qualitative real-time PCR and its associations with age, sex, anatomic location, lymph node metastasis, tumor thickness, ulceration, mitotic index, necrosis, lymphovascular invasion, and tumor-infiltrating lymphocytes were analyzed." (PMID 31890008, 2019). "Hypomethylation and increased expression of MIR146B, as well as decreased target genes expression, were significantly associated with features related to poor prognosis (advanced clinical stage, lymph node metastasis, and extrathyroidal extension) and BRAF mutation." (PMID 30454026, 2018). "According to several studies, BRAF mutations are associated with poor prognostic factors, including larger tumor size, older age, male gender, extrathyroidal extension, tumor multifocality, lymph node metastasis, advanced tumor stage, and recurrence." (PMID 29312581, 2017). "PTCs with TERT+BRAF mutation had lateral lymph node metastasis more frequently than PTCs with BRAF mutation alone (OR = 22.557, 95% CI = 2.181–233.294) and demonstrated non-parallel orientation on US more frequently than PTCs without any mutation (OR = 11.282, 95% CI = 1.008–126.270)." (PMID 29312581, 2017). "Furthermore, the multivariate logistic regression analysis showed that lymph node metastasis and BRAF V600E mutation were independent factors that predicted tumor prognosis." (PMID 24396464, 2014).